CAV3 (caveolin 3)
Diseases named in the same sentence as CAV3 in open-access papers (continued):
Sharing a sentence is not in itself a finding about the gene and the disease.
Arrhythmia (10 papers, 2014 to 2026). Any cardiac rhythm other than the normal sinus rhythm. "Beyond risk prediction, increasing evidence links Cav-3/caveolae to HF-relevant pathophysiology, including arrhythmia susceptibility and insulin-signaling defects in ischemic or metabolic heart disease—both potential treatment targets." (PMID 41143172, 2025). "This work aims to predict the risk of developing cardiac arrhythmias in patients with CAV3 mutations located in different domains of the protein." (PMID 38256054, 2024). "Although dysfunctional Nav1.5 under I/R caused lethal cardiac arrhythmias, it was unclear if activated Cav-3 SUMOylation by PIASy alters Nav1.5 abundance after I/R." (PMID 36229865, 2022). "The arrhythmia mechanism associated with change of CAV-3 expression." (PMID 35329921, 2022). "This review highlights the underlining mechanisms of caveolin-3 in arrhythmia." (PMID 35329921, 2022). "Indeed, adenovirus-mediated overexpression of KCNJ2 was recently used to generate more mature hiPSC-CMs to study the arrhythmia mechanism of an LQT9 CAV3 mutation." (PMID 28883014, 2017). "Overwhelming evidence has suggested that CAV-3 gene mutation results in not only slower activation and recovery of IKv4.2, which could cause a reduction of Ito at physiological heart rates, but decreased IKv4.2, which contributes to cardiac arrhythmia." (PMID 35329921, 2022). "The functional significance of the caveolin-3 has proved that caveolin-3 overexpression or knockdown contributes to the occurrence and development of arrhythmias." (PMID 35329921, 2022). "Further basic science research and eventual randomized clinical trials are needed to define the precise mechanisms and therapeutic potential of caveolin-3 in patients with arrhythmias." (PMID 35329921, 2022). "Five mice died shortly after ischemia/reperfusion because of fatal cardiac arrhythmia in the in vivo experiments (control, 1; Ex-4 administration, 2; Cav-3 KO control, 1; Cav-3 KO Ex-4 administration, 1)." (PMID 25194961, 2014). "Caveolin-3 dysfunctions have been responsible for inherited arrhythmias." (PMID 35329921, 2022). "The importance of caveolin-3 changes in arrhythmias and downstream microdomain dysregulation may have important implications for arrhythmia generation." (PMID 35329921, 2022). "The importance of Cav3 changes in HF and downstream microdomain dysregulation may have important implications for arrhythmia generation." (PMID 30473666, 2018). "Male, but not female, CIH rats have altered expression of Cav3, Cacna1c, Cacnb2, Kcne5, Kcnd2, and Hcn2 which may preferentially predispose postnatal males to develop arrhythmia." (PMID 38981849, 2024). "Moreover, a study has revealed that caveolin-3 participated in common early anterograde trafficking mechanism of the NaV1.5-Kir2.1 channelsome, which may have contributed to the potential for arrhythmias." (PMID 35329921, 2022).
caveolinopathies (10 papers, 2012 to 2024). "Mutations in the CAV3 gene can give rise to a family of neuromuscular disorders called caveolinopathies." (PMID 38256054, 2024). "In humans, the majority of caveolinopathies often refers to a wide spectrum of skeletal muscle disorders and only recently mutations in caveolin-3 were associated to cardiac pathologies including LQTS and SIDS and cardiomyopayhies." (PMID 24917393, 2014). "Caveolin‐3 (Cav3) is regarded as a crucial component of muscle physiology as underscored by mutations within the CAV3 gene that result in numerous pathologies, commonly referred to as caveolinopathies." (PMID 37671684, 2023). "Muscle diseases caused by mutations in the CAV3 gene are called caveolinopathies." (PMID 30153853, 2018). "The set of diseases characterized by reduced levels of Cav3 are collectively called caveolinopathies." (PMID 33228026, 2020). "The role of Cav3 at the NMJ may have important implications for pathological processes in various caveolinopathies in which the level of Cav3 decreases in the muscle membrane." (PMID 33228026, 2020). "In caveolinopathy, mutant muscle fibres are known to present with absence of sarcolemmal CAV3 (drastically reduced immunoreactivity)." (PMID 30153853, 2018).
distal myopathy (9 papers, 2009 to 2022). Distal myopathy refers to a group of muscle diseases which share the clinical pattern of predominant weakness and atrophy beginning in the feet and/or hands. "The mutation Ala46Thr in Cav3 that turned out to cause a reduced Cav3 expression leads to distal myopathy with hypertrophy of the calf muscles." (PMID 33228026, 2020). "LGMD-1C, distal myopathy and RMD are degenerative, skeletal muscle-associated diseases associated with mutations in CAV3." (PMID 29202928, 2017). "A distal myopathy panel may also want to include traditional LGMD genes CAPN3 and CAV3 as these can also result in a distal myopathy phenotype." (PMID 36313509, 2022). "So far, 18 mutations in Cav3 have been associated with human dystrophies such as limb-girdle muscular dystrophy 1C (LGMD-1C), hereditary rippling muscle disease (RMD), hyperCKemia, and distal myopathy, whereas Cav3 overexpression is observed in Duchenne muscular dystrophy." (PMID 33228026, 2020). "CAV3 mutations manifest in several human diseases, for example limb girdle muscular dystrophy (LGMD), rippling muscle disease (RMD), hyperCK(creatine kinase)emia, distal myopathy, hypertrophic cardiomyopathy, arrhythmogenic-long-QT syndrome and sudden-infant-death syndrome." (PMID 29202928, 2017).
Hyperglycemia (9 papers, 2015 to 2025). An increased concentration of glucose in the blood. "The advancement of the current study is that hyperglycemia-induced inhibition of eNOS activation is associated with caveolae dysfunction and reduced Cav-3 expression." (PMID 27733157, 2016). "In summary, the results of current study demonstrate that hyperglycemia-induced inhibition of eNOS activity is associated with caveolae dysfunction and reduced Cav-3 expression in diabetic hearts." (PMID 27733157, 2016). "We next investigated whether hyperglycemia-induced inhibition of eNOS activation might be associated with reduced cav-3 expression." (PMID 27733157, 2016). "Mice preconditioned with REM have been reported to display a much lower risk of myocardial injury following I/R procedures, whereas hyperglycemia-induced oxidative stress could diminish REM cardioprotection by damaging the Caveolin-3-regulated PI3K/Akt and JAK2/Stat3 signaling pathways." (PMID 34612779, 2021). "Thus, suppression of hyperglycemia-induced oxidative stress may restore eNOS activity and Cav-3 expression in diabetic hearts, and restoring the Cav-3 expression or increasing the association of eNOS and Cav-3 may attenuate eNOS uncoupling." (PMID 27733157, 2016). "In the present study, we have demonstrated that hyperglycemia-induced oxidative stress is accompanied with reduced Cav-3 expression and eNOS activation in diabetic hearts, which is consistent with our previous findings." (PMID 27733157, 2016). "Thus, hyperglycemia-induced oxidative stress abrogates RPC cardioprotection by impairing Cav-3-modulated PI3K/Akt and JAK2/STAT3 signaling." (PMID 31583053, 2019). "Hyperglycemia may suppress myocardial caveolin-3 in a PKCβ2 dependent manner and H9c2 cardiomyoblast caveolin-3 in an oxidant-dependent manner, while hyperinsulinemia also depresses caveolar caveolin-3 in H9c2 cells." (PMID 29202762, 2017). "Hyperglycemia also acutely depresses caveolin-3 expression in cardiac myoblasts, and hyperinsulinemia suppresses caveolar levels of caveolin-3 in H9c2 myoblasts, which may dysregulate Akt-dependent InsR signaling." (PMID 29202762, 2017). "Hyperglycemia-induced inhibition of eNOS activity might be consequences of caveolae dysfunction and reduced Cav-3 expression." (PMID 27733157, 2016). "In the present study, we hypothesize hyperglycemia-induced oxidative stress promotes caveolae dysfunction and impairs Cav-3/eNOS signaling." (PMID 27733157, 2016). "Moreover, it has been demonstrated that hyperglycemia reduces the expression of caveolin-3 in the cardiomyocytes through protein kinase C β2 activation leading to diastolic cardiac dysfunction." (PMID 26152221, 2015). "Thus, hyperglycemia-induced oxidative stress may have increased Cav-3 degradation through activating a ubiquitin-proteasome system in the diabetic hearts or in high-glucose-stimulated cardiomyocytes, though further study is merited to test this hypothesis." (PMID 31583053, 2019).
myocardial ischemia (8 papers, 2013 to 2025). A disorder of cardiac function caused by insufficient blood flow to the muscle tissue of the heart. "Previous study demonstrated that overexpression of CAV3 improved mitochondrial dysfunction in myocardial ischemia/reperfusion injury through activation of the Akt signaling pathway." (PMID 38671439, 2024). "Recently, SF-PreCon was reported to inhibit COX-2 expression through the induction of Cav-3 in myocardial ischemia/reperfusion injury." (PMID 29152109, 2017). "Recently, it has been demonstrated that the cardioprotective effects of isoflurane bolus administration against myocardial ischemia are abolished when caveolae formation is disrupted or Cav-3 is knocked out." (PMID 29152109, 2017). "Recently, SF-PreCon was reported to attenuate myocardial ischemia/reperfusion injury via cavelin-3 (Cav-3)-dependent COX-2 inhibition." (PMID 29152109, 2017). "We also reported that myocardial ischemia/reperfusion-induced activation of p38 and ERK MAPKs was associated with changes in subcellular cholesterol levels and caveolin-3 distribution." (PMID 27441649, 2016). "Sevoflurane also induces preconditioning and attenuates myocardial ischemia/reperfusion injury via caveolin-3-dependent cyclooxygenase-2 inhibition, AMP-activated protein kinase, and antioxidative effects in experimental studies." (PMID 26583144, 2015). "In addition, using a rat model of myocardial ischemia involving LAD ligation, we demonstrated that GTPs treatment for 2 weeks efficiently protected infarcted myocardium of LAD-ligated rats from reduced Cav-3 protein levels." (PMID 24251870, 2013).
sudden infant death syndrome (8 papers, 2008 to 2025). Unexpected death in infancy which remains unexplained following autopsy, review of the medical history, and investigation of the death circumstances and death scene. "In addition, caveolin-3 mutations seem important in some cases of sudden infant death syndrome." (PMID 23585895, 2013). "In addition, three distinct CAV3 mutations (V14L, T78M, and L79R) affecting late INa in a similar way were identified in sudden infant death syndrome (SIDS)." (PMID 34572065, 2021). "Mutations in four of these genes, i.e. GPD1L, MOG1, SNTA1, CAV3 have been linked with AF and long QT syndrome (LQTS), Brugada syndrome (BrS) or sudden infant death syndrome (SIDS)." (PMID 28837624, 2017).
Duchenne muscular dystrophy (7 papers, 2013 to 2024). Duchenne muscular dystrophy (DMD) is a neuromuscular disease characterized by rapidly progressive muscle weakness and wasting due to degeneration of skeletal, smooth and cardiac muscle. "A significant increase in the number of caveolae at the sarcolemma is associated with the over-production of caveolin-3 in patients with Duchenne muscular dystrophy (DMD)." (PMID 37327338, 2023). "High numbers of caveolae have been identified in muscle fibers from Duchenne muscular dystrophy, whereas mutations in the caveolin 3 gene cause multiple forms of muscle pathologies." (PMID 25799323, 2015). "Intriguingly, the fragile muscle fibers from patients with Duchenne muscular dystrophy contain elevated numbers of caveolae-like vesicles, and mutations in the muscle-specific caveolar protein caveolin-3 (Cav3) cause multiple forms of muscle pathology." (PMID 24052812, 2013). "TRPC1 and caveolin-3 protein levels have been shown to increase in the skeletal muscle from mice with Duchenne muscular dystrophy, and TRPC1 is activated by ROS in an Src kinase-dependent manner." (PMID 34174803, 2021). "Altered expression of Caveolin-3 is also observed in Duchenne’s muscular dystrophy, which is likely a part of the pathological process leading to muscle weakness." (PMID 33228026, 2020). "Altered expression of caveolin-3 has also been detected in Duchenne muscular dystrophy, which may be a part of the pathological process leading to muscle weakness." (PMID 39201459, 2024). "Duchenne muscular dystrophy fibers were shown in numerous studies to contain elevated numbers of caveolae, but this important finding was also attributed to secondary effects of alterations in Cav3 expression levels." (PMID 24052812, 2013).
epilepsy (7 papers, 2012 to 2024). A brain disorder characterized by episodes of abnormally increased neuronal discharge resulting in transient episodes of sensory or motor neurological dysfunction, or psychic dysfunction. "Aberrant Cav3 activity is associated with a range of neurological disorders, including neuropathic pain and epilepsy." (PMID 37082241, 2023). "Despite the low potency of ω-Avsp1a, its selectivity for CaV3.1/CaV3.3 over CaV3.2 makes it a useful pharmacological tool for dissecting out the role of these different CaV3 subtypes in disorders such as epilepsy or pain." (PMID 35625803, 2022). "Considering our present findings, and that Cachd1 was identified as a modulator of CaV3 activity, it may serve as a potential target in diseases such as epilepsy and pain." (PMID 36077281, 2022).
ischemia (7 papers, 2012 to 2025). A hypoperfusion of the BLOOD through an organ or tissue caused by a PATHOLOGIC CONSTRICTION or obstruction of its BLOOD VESSELS, or an absence of BLOOD CIRCULATION. "Cav3 has been shown to play a critical role in autophagy, protecting the cardiac muscle from damage after ischemia and reperfusion." (PMID 33228026, 2020). "The heart of Cav3 KO mice show increased contractile dysfunction and cell damage following ischemia." (PMID 33228026, 2020). "We observed in the present study that administration of AS-1 immediately before reperfusion after ischemia significantly attenuated I/R-induced decreases in the numbers of caveolae in the plasma membrane and distribution of Cav-3." (PMID 28291255, 2017). "Fortunately, a number of alternative approaches taking advantage of the direct link between Cav-3 and cardioprotection from ischemia are being developed and identified." (PMID 22934034, 2012). "In doing so, the current understanding of and potential of Cav-3 therapeutics in offering cardioprotection in the classic sense, from ischemia, and protection from development of cardiovascular disease is presented." (PMID 22934034, 2012). "The overexpression of Cav3 has been shown to protect the heart from ischemia." (PMID 33228026, 2020). "Therefore, given the central role of Cav-3 in ischemic preconditioning, Cav-3 presents itself as an interesting therapeutic target for inducing cardioprotection from ischemia." (PMID 22934034, 2012). "Furthermore, FAT10stabilizes Caveolin-3 (Cav3), whose increased expression leads to a decreasein cardiomyocyte INaL by reducing S-nitrosylation of Nav1.5, and may also play arole in decreasing ischemia-induced arrhythmias." (PMID 40630435, 2025).
myocardial infarction (7 papers, 2013 to 2024). Gross necrosis of the myocardium, as a result of interruption of the blood supply to the area, as in coronary thrombosis. "Additionally, caveolin-3+ EV correlated with CK-MBmax, a known marker of myocardial infarction severity." (PMID 34805303, 2021). "Caveolin-3+ EV also correlated with time from reperfusion to blood sampling, indicating a time dependent release, previously reported for conventional biomarkers of myocardial infarction." (PMID 34805303, 2021). "This time-dependent release after myocardial infarction further supports our hypothesis, that caveolin-3+ EV were released in response to ischemic myocardial injury and that caveolin-3+ EV are increased at least during the first day after myocardial infarction." (PMID 34805303, 2021).
breast cancer (6 papers, 2013 to 2023). A primary or metastatic malignant neoplasm involving the breast. "Cav-3 has been less studied in breast cancer, and the loss of its expression can form an antitumor microenvironment." (PMID 37828916, 2023). "In addition, it has been shown that loss of Caveolin-3 can induce a lactogenic microenvironment that is protective against mammary tumor formation." (PMID 23658834, 2013). "These analyses can provide preliminary information on the role of CaV3 in tumor transformation of breast cancer from pre-neoplastic and neoplastic lesions." (PMID 36790286, 2023). "Studies have shown that with the progression of breast cancer, the positive rate of Cav-3 in epithelial tissues decreases, while the positive rate of Cav-2 in interstitial tissues increases." (PMID 37828916, 2023). "Comparatively, CAV2 and CAV3 were less studied in cancer, but CAV3 have showed a better potential in correlating to breast cancer development." (PMID 34513683, 2021). "CaV3 mRNA expression in breast cancer is still poorly understood." (PMID 36790286, 2023). "Therefore, Cav-2, Cav-3 and Cav-1 can also act as related regulatory factors in breast cancer progression and play dual roles in cancer inhibition and promotion." (PMID 37828916, 2023). "There are still few studies on the role of Cav-3 in breast cancer." (PMID 37828916, 2023). "The Cav proteins include Cav-1, Cav-2 and Cav-3, among which Cav-1 has attracted the most attention as a tumor suppressor and promoting factor affecting the proliferation, apoptosis, migration, invasion and metastasis of breast cancer cells." (PMID 37828916, 2023). "However, recent studies have found that TREK1 is overexpressed in prostate cancer (PC) cells, CAV-3 is upregulated in anaplastic thyroid carcinoma, and Bnip3 levels are higher in breast cancer (BC) and NSCLC." (PMID 35805104, 2022). "The statistical results showed that CAV1, CAV2, CAV3, CAVIN1, and CAVIN2 were significantly less expressed in breast cancer tissues than in normal ones." (PMID 34513683, 2021). "Our results elucidated that lower expression of CAV3, CAVIN1, and CAVIN2 significantly related to OS of patients with Luminal A breast cancer." (PMID 34513683, 2021). "The breast cancer cell line MCF-7 expresses CaV3.1 and CaV3.2, which seem to be involved in proliferation." (PMID 27342111, 2016). "The expression of T-type voltage-dependent Ca2+ channels (Cav3) has been previously observed in breast cancer, but their expression and subcellular localization were not evaluated in pre-neoplastic lesions." (PMID 36790286, 2023). "In in vivo experiments, when Cav-3 is not expressed, the anti-mammary tumor formation ability of mice is significantly enhanced, while the growth of mammary tumors is inhibited and lung metastasis is significantly reduced." (PMID 37828916, 2023). "However, it should be noticed that the expression levels of CAV3 and CAVIN4 in both cancer tissues and normal tissues were rather low, indicating a limited role of these two proteins in the tumorigenesis and progression of breast cancer." (PMID 34513683, 2021).